DDIT3 (DNA damage inducible transcript 3)
Diseases named in the same sentence as DDIT3 in open-access papers (continued):
Sharing a sentence is not in itself a finding about the gene and the disease.
cervical carcinoma (22 papers, 2014 to 2024). A carcinoma arising from either the exocervical squamous epithelium or the endocervical glandular epithelium. "In conclusion, our findings indicated that 20(S)-GRh2 might promote ERs-related apoptosis of cervical cancer cells by regulating the DDIT3-based targets’ signal pathway." (PMID 36431966, 2022). "Induction of ER-stress in cervical carcinoma cells (HeLa) by glucose deprivation showed early upregulation of ATF4 and other target genes of this stress response pathway such as DDIT3, GADD34, ATF3, and EIF4EBP1 at 24 h." (PMID 33413684, 2021). "In the same way, the effect of metformin on DDIT3 gene expression in cervical cancer cells has not been fully elucidated." (PMID 37371530, 2023). "Combined protein–protein interaction network, hub gene screening, and qPCR validation data showed that ERs-related genes (ATF4 and DDIT3) and the downstream apoptotic genes (JUN, FOS, BBC3, and PMAIP1) were potential novel targets of 20(S)-GRh2-inducing cervical cancer cell apoptosis." (PMID 36431966, 2022). "It implies that ERs-related genes (ATF4 and DDIT3) and downstream apoptosis genes (JUN, FOS, BBC3, and PMAIP1) are the potential targets of 20(S)-GRh2 and might be interacting with each other to be involved in the apoptosis induction in cervical cancer cells." (PMID 36431966, 2022).
osteosarcoma (22 papers, 2004 to 2024). A usually aggressive malignant bone-forming mesenchymal neoplasm, predominantly affecting adolescents and young adults. "In this study, we confirmed a strong WT drug-induced DDIT3 upregulation also in osteosarcoma cells." (PMID 38201265, 2023). "The genes of four TFs (DDIT3, SP7 and CREB3L1) were significantly activated in C5_osteoblastic OS cells, and these TFs have been shown to be expressed in osteosarcoma in previous studies." (PMID 34367994, 2021). "In a study of osteosarcoma, after TRIM2 was silenced, DDIT3 was significantly upregulated." (PMID 36051486, 2022).
renal fibrosis (22 papers, 2015 to 2026). A final common manifestation of a wide variety of chronic kidney diseases characterized by glomerulosclerosis and tubulointerstitial fibrosis. "Recent studies corroborate roles for DDIT3 in renal fibrosis and ER stress-driven injury." (PMID 41481573, 2026).
leukemia (21 papers, 2012 to 2026). A malignant (clonal) hematologic disorder, involving hematopoietic stem cells and characterized by the presence of primitive or atypical myeloid or lymphoid cells in the bone marrow and the blood. "Therefore, the identification of C/EBPα-DDIT3 axis as a regulator of UPR signaling during myeloid differentiation helps us better understand the physiological mechanisms by which HSPCs with CEBPA deficiency avoid leukemia transformation." (PMID 38475919, 2024). "Here, we provided further data on the correlation between DDIT3 and C/EBPα, which are involved in the terminal UPR signaling and leukemogenesis respectively, and their pivotal role in leukemia prevalence and drug sensitivity." (PMID 38475919, 2024).
viral infection (21 papers, 2006 to 2025). "Strong IFN signaling responses observed in acute viral infection are often accompanied by induction of genes associated with cell stress (DDIT3/CHOP), apoptosis (PMAIP1/Noxa), and general inflammatory chemokines (CXCL10, CXCL12, and CCL5)." (PMID 38440980, 2024). "The use of 2-DG has disclosed the central function of glucose metabolism in bacterial and viral infection by showing in the latter model the lethality associated with 2-DG treatment by a mechanism involving type I IFN signaling and Ddit3/CHOP." (PMID 28674530, 2017). "In addition, BVDV infection induced higher mRNA and protein levels of DNA damage-inducible transcript 3 (DDIT3), which inhibited type I IFN production by regulating MAVS degradation during viral infection in MDBK cells and in mice." (PMID 37900320, 2023). "Using a cutoff of greater than 30% increase in viral infection normalized to cell viability in two independent screens, we identified HSPA5, TMED2, SPCS2, and DDIT3 as factors whose overexpression increased DENV infection, indicating rate limitation associated with these important proviral factors." (PMID 29451494, 2018).
Parkinson disease (20 papers, 2013 to 2025). A progressive degenerative disorder of the central nervous system characterized by loss of dopamine producing neurons in the substantia nigra and the presence of Lewy bodies in the substantia nigra and locus coeruleus. "Echinacoside, an active component of Cistanche, has been identified through target gene analysis to interact with specific targets (NTRK1, MAPK1, SNCA, DDIT3) in Parkinson’s disease model cells, which are also DEGs in our study." (PMID 39221152, 2024). "Post-mortem studies have identified ATF4 and DDIT3 in dopaminergic neurons of Parkinson’s patients." (PMID 37353587, 2023). "Additionally, it modulates the ROS/ATF3/CHOP pathway to reduce the expression of apoptotic genes DDIT3 (CHOP) and SNCA (α-synuclein, α-syn), thereby inhibiting apoptosis in Parkinson’s disease cell models." (PMID 39221152, 2024). "Additionally, in in vitro and in vivo models of neurotoxin-induced parkinsonism, in which neurotoxins such as 6-hydroxy-dopamine (6-OHDA) and MPTP are typically administered, the genetic ablation of Ddit3 (CHOP) and overexpression of XBP1s protect neurons from neurotoxin-induced cell death." (PMID 35682574, 2022).
Alzheimer disease (17 papers, 2013 to 2024). A progressive, neurodegenerative disease characterized by loss of function and death of nerve cells in several areas of the brain leading to loss of cognitive function such as memory and language. "According to the in silico prediction (position 49 in 753 models), the lignans can act DNA damage-inducible transcript 3 protein (C/EBP homologous protein, CHOP) which has been proposed as a target of treatments for some neurodegenerative diseases as Alzheimer’s diseases." (PMID 30551576, 2018). "However, in the Alzheimer’s disease specific TMA, we only obtained significant data for TOPORS and DDIT3." (PMID 29541381, 2018). "Worth a mention is the downregulation of DDIT3, SMC4, and TENM4 in replicative senescence of human fibroblasts; the upregulation of SMC4 and MCM7 after vitamin C treatment; the upregulation of HOXB3 and TENM4 in Alzheimer’s disease; and the deregulation of DDIT3 and SMC4 in COVID-19 disease." (PMID 36982191, 2023).
diabetic nephropathy (17 papers, 2014 to 2026). "DDIT3, GADD45A, THBS2, CCL2, and CSF1R showed consistent expression trends across platforms, and are known mediators of inflammation, extracellular matrix remodeling, and stress responses in diabetic kidney disease." (PMID 41481573, 2026).
liver fibrosis (16 papers, 2013 to 2025). "This included genes associated with metabolism (Fabp1, Insr), genes associated with cell stress (Atf6, Ddit3, and Eif2ak3), genes associated with liver fibrosis (Hgf, Sp1, and Timp1) and genes associated with the inflammatory response (Tnf, Ptpn22, and Pparg)." (PMID 28686204, 2017). "Accordingly, CHOP expression was measured in liver tissue from naïve and CCl4-treated mice, and a significant upregulation of Ddit3 mRNA and CHOP protein expression was found in mice with advanced liver fibrosis compared to control." (PMID 34336828, 2021).
liver cancer (15 papers, 2010 to 2025). An epithelial or non-epithelial malignant neoplasm that arises from the liver. "Since DDIT3 (alsoknown as CHOP) has been implicated in oncogenic progression of hepatocytes leadingto liver cancer, this might be one ofthe connecting links between HBV-induced DDR, cirrhosis, and oncogenesis." (PMID 41070968, 2025). "By analyzing RNA-seq data from TCGA and GTEx, we discovered that ATF3, ACSL1, LPIN1, and DDR2 were significantly downregulated while DDIT3 was upregulated in liver tumor compared with normal tissues, implying that these five genes might be associated with liver cancer." (PMID 37580343, 2023).
ZIKV infection (15 papers, 2018 to 2025). "Ddit3 has been shown in the adult to contribute to retinal ganglion cell death and consistent with the increase in Ddit3 seen here, and the pathology seen at later stages of ZIKV-infection in a similar model is loss of the RGC layer of the retina." (PMID 37022660, 2023). "Both DDIT3 and GADD34 were less expressed in PKR−/− cells than in WT cells during DENV4 and ZIKV infection." (PMID 37732809, 2023). "Selected genes blocking cell growth (DDIT3, GADD45B, and CDKN2B) were significantly upregulated by ZIKV infection." (PMID 30228241, 2018).
ischemia (14 papers, 2013 to 2025). A hypoperfusion of the BLOOD through an organ or tissue caused by a PATHOLOGIC CONSTRICTION or obstruction of its BLOOD VESSELS, or an absence of BLOOD CIRCULATION. "The tissues of cerebral ischemic scars were taken for IHC staining and Western blotting, and the expressions of FOS, DDIT3, DUSP1 and NFIL3 after ischemia were detected." (PMID 38384585, 2024).
ischemic stroke (14 papers, 2015 to 2026). A stroke disorder caused by obstruction of blood flow to the brain, due to thrombotic (local blood clot formation) or embolic (due to a blood clot or other material traveling from another site) event. "Several studies have proposed that brain ischemia impairs ER function and activates the UPR, since the expression of target genes of the three UPR branches, including Grp78, Pdia4 and Ddit3/Chop were found up-regulated after ischemic stroke." (PMID 31683519, 2019). "These in silico findings propose that the putative effects of ketamine on comorbid ischemic stroke and depression may involve modulation of multiple pathways, with IL1RN and DDIT3 as potential key contributors." (PMID 41849332, 2026).
retinal degeneration (14 papers, 2010 to 2025). Degeneration of the retina. "Based on the fact that retinal degeneration associated with high dose of HMOX1 levels is correlated with upregulation of Ddit3 expression, we finally evaluated whether the induction of DDIT3 might mediate HMOX1-induced photoreceptor degeneration." (PMID 33691741, 2021).
round cell liposarcoma (14 papers, 2009 to 2025). A poorly differentiated liposarcoma, characterized by the presence of solid sheets of primitive round mesenchymal cells and the absence of myxoid stroma. "DDIT3 is found as a part of the fusion oncogene FUS-DDIT3 that is causal for the development of myxoid/round-cell liposarcomas (MLS/RCLS)." (PMID 20017906, 2009). "The presence of DDIT3 gene alteration can aid in diagnosing myxoid/round cell liposarcoma (with over 95% of cases showing CHOP/FUS fusion)." (PMID 40308488, 2025). "On the other hand, the DDIT3 gene is known to be rearranged in myxoid/round cell liposarcomas, which can fuse with either EWSR1 or FUS, and these fusions serve as diagnostic markers for this entity." (PMID 38275873, 2024). "DDIT3 is also a part of a fusion oncogene critical for the development of myxoid/round cell liposarcoma (MLS/RCLS)." (PMID 20017906, 2009). "For example, FUS and DNA damage-inducible transcript 3 are able to form a fusion oncogene FUS-CHOP, which increases the invasive capability of human mucus-like and round cell liposarcoma cells." (PMID 30736838, 2019). "FUS, was first identified in human myxoid and round cell liposarcomas as an oncogenic fusion protein with a stress-induced DNA-binding transcription factor, CCAAT enhancer-binding homologous protein (CHOP, also known as GADD153 or DDIT3)." (PMID 31238957, 2019). "Additional FISH assays for WT1, CHN and DDIT3 (3' partners of EWSR1 in desmoplastic round cell tumor, extraskeletal myxoid chondrosarcoma and round cell liposarcoma, respectively) were negative." (PMID 20598147, 2010).
steatosis (14 papers, 2011 to 2025). Increased lipid within the cytoplasm of cells. "Alternatively, other investigations identified the pro-lipogenic role of certain UPR targets such as CHOP (also known as Ddit3), underscoring the complex integration of the various components of the UPR in the development of steatosis." (PMID 30733237, 2019).
fibrosarcoma (12 papers, 2008 to 2025). A malignant mesenchymal fibroblastic neoplasm affecting the soft tissue and bone. "To investigate the specific effects of cytoplasmic and nuclear DDIT3 we constructed HT1080 fibrosarcoma clones with stable expression of the DDIT3morEGFP recombinant protein." (PMID 22496745, 2012). "To explore the link between the UPR and circadian oscillation we characterized TXNIP and DDIT3 in both SAHA/JQ1-treated UPS and fibrosarcoma cells." (PMID 30382078, 2018).
ocular hypertension (12 papers, 2017 to 2025). Abnormally high intraocular pressure. "Given Ddit3/Jun deletion protected most RGC somas after chronic ocular hypertension, it remained important to determine whether surviving D2.Ddit3/Jun−/− RGC somas retained gross physiological function." (PMID 41397991, 2025). "It is possible that DDIT3 deficiency can delay axonal degeneration after an ocular hypertensive injury, but not prevent degeneration after long term ocular hypertensive insult or severe mechanical injury." (PMID 31632741, 2019). "It is possible DDIT3 and JUN act together, playing redundant and compensatory roles to integrate somal and axonal degeneration cascades in the context of ocular hypertension." (PMID 41397991, 2025). "Further study of other signaling molecules suggested to have a role in axonal degeneration such as DDIT3, IKK, GSK3, or PHR1 will be necessary to understand the signaling pathways for axonal degeneration after ocular hypertension." (PMID 28726785, 2017). "DDIT3/JUN controlled the majority of RGC somal death in ocular hypertensive DBA/2 J mice but did not control axonal degeneration." (PMID 41397991, 2025). "Therefore, it will be important to test the role of Jun and Ddit3 in a chronic, age-related model of ocular hypertension, the DBA/2 J mouse, to determine if Jun and Ddit3 are critical for glaucomatous ocular hypertensive injury." (PMID 28969695, 2017). "Therefore, Ddit3/Jun deletion did not substantially alter the profile of ocular hypertension typical of the DBA/2J model." (PMID 41397991, 2025). "Interestingly, Ddit3/Jun deletion did not prevent ocular hypertension-induced shrinkage of the RGC soma, suggesting surviving RGCs are likely injured and/or undergoing metabolic stress." (PMID 41397991, 2025). "Therefore, identifying the ocular hypertension-induced upstream regulator of both JUN and DDIT3 may be an important step in determining an upstream mechanism driving glaucomatous RGC death." (PMID 31632741, 2019).
osteoarthritis (12 papers, 2019 to 2026). A noninflammatory degenerative joint disease occurring chiefly in older persons, characterized by degeneration of the articular cartilage, hypertrophy of bone at the margins and changes in the synovial membrane. "In the present study, compared to the normal group, DDIT3 expression was down-regulated in advanced osteoarthritis, we hypothesized that the decreased autophagy end of osteoarthritis could be connected to the downregulation of DDIT3 expression." (PMID 38175691, 2024).
Stroke (12 papers, 2014 to 2025). Sudden impairment of blood flow to a part of the brain due to occlusion or rupture of an artery to the brain. "Flowchart illustrating the protective effect of zinc on stroke through various stages: GWAS analysis and NHANEs database, bioinformatic analysis, diagnostic model, pathway analysis showing autophagy, and genes involved (RELA, TNFSF10, NFE2L2, FADD, DDIT3, CFLAR)." (PMID 40969765, 2025). "The key genes encompass critical pathways such as autophagy (e.g. NFE2L2, DDIT3, NAMPT), apoptosis (e.g. CFLAR, FADD) and NF-κB signaling (e.g. RELA, TNFSF10), suggesting a multifactorial involvement of these pathways in stroke pathophysiology." (PMID 40969765, 2025).
lung adenocarcinoma (11 papers, 2014 to 2025). A carcinoma that arises from the lung and is characterized by the presence of malignant glandular epithelial cells. "The TCGA database confirmed that the levels of DDIT3 and ATF3 in Lung squamous cell carcinoma (LUSC) and lung adenocarcinoma (LUAD) tumor tissues were significantly decreased compared with normal tissues." (PMID 38244586, 2024).
asthma (9 papers, 2017 to 2024). "The CHOP protein (also known as GADD153 or DDIT-3) is an important signal molecule in ER stress, and its specific mechanism in asthma has been gradually studied." (PMID 35559240, 2022).
Hypertension (9 papers, 2015 to 2025). The presence of chronic increased pressure in the systemic arterial system. "Their transcription levels correlate with the transcription levels of several genes encoding transcription factors associated with the response to oxidative stress, including transcription factors associated with hypertension (Arnt, Atf4, Ddit3, Foxo1)." (PMID 39594444, 2024). "Moreover, global deletion of the ER stress chaperone Ddit3 (CHOP) prevents vitamin D-deficiency-induced renin-dependent hypertension in mice, and their macrophages are unable to activate JG cell renin production." (PMID 32968066, 2020).
bladder cancer (8 papers, 2013 to 2023). "We also discovered that ER stress component, like HSPA5, ERN1, ATF4 and DDIT3, increased when the human bladder cancer cells were treated with BIX-01294." (PMID 25685062, 2015). "Bladder cancer, proximal tubule bicarbonate reclamation, steroid hormone biosynthesis, SLE, and viral protein interaction with cytokine and cytokine receptors had significant enrichment in the high DDIT3 subgroup." (PMID 38013304, 2023). "Since DDIT3 also modulates other apoptotic proteins such as death receptors in the extrinsic pathway, we cannot exclude the role of extrinsic pathway in the apoptosis induction by BIX-01294 in bladder cancer cells." (PMID 25685062, 2015).
chronic kidney disease (7 papers, 2016 to 2025). Impairment of the renal function secondary to chronic kidney damage persisting for three or more months. "DDIT3 (DNA damage-inducible transcript 3) expression is positively correlated with arterial calcium content and intima-media thickness (IMT) in children with chronic kidney disease (CKD), suggesting it contributes to accelerated arterial calcification and remodeling." (PMID 40607379, 2025).